JAK2 (Janus kinase 2)
Diseases named in the same sentence as JAK2 in open-access papers (continued):
Sharing a sentence is not in itself a finding about the gene and the disease.
tumor (continued). "Dp may exert its anti-TNBC effects by downregulating PD-L1 expression in TNBC cells and exosomes through the JAK2/STAT3 signaling pathway, potentially restoring T cell activity and modifying the tumor microenvironment." (PMID 39781272, 2024). "Notably, we observed JAK1, JAK2, STAT3 were all located in ATC tumor cells, suggesting a crucial role of JAK1/2-STAT3 activation in maintaining malignant features of ATC tumor cells." (PMID 38336839, 2024). "In addition, W. coagulans MZY531 regulates the Bax/Bcl-2/caspase-3 and JAK2/STAT3 apoptosis pathways and PI3K/AKT/mTOR pathways, as well as TGF-β/SMAD4 autophagy pathways, thereby attenuating tumor growth." (PMID 39459634, 2024). "CASP3, SRC, ESR1, JAK2, PRKACA, HSPA8 and CAT exhibited stronger interactions with other factors, suggesting that they may be the key targets for tumor treatment." (PMID 38675723, 2024). "By pre-treating tumor-bearing mice with a JAK2 inhibitor, we were able to transiently mask the systemic toxicity of a tumor-targeted IL12 without compromising the anti-cancer activity." (PMID 38448543, 2024). "In addition, we employed qRT‐PCR to assess the RNF122, JAK2, and STAT3 expression levels in tumor samples and performed correlation analysis." (PMID 39218810, 2024). "However, sustained activation of JAK2/STAT3 signaling had been found in many solid tumors, such as breast cancer, which promoted solid tumorigenesis, tumor growth, angiogenesis, host immune evasion, apoptosis resistance, carcinogenesis, and metastasis." (PMID 38420199, 2024). "Next, CPL304110 selectivity was analyzed on seven kinases; the results showed that CPL304110 had the highest activity against kinases that share homology with FGFRs (KDR and PDGFRβ) and others that play an important role in tumor development and progression (AURKA, FLT3, IGF1R, JAK2, and TRKA)." (PMID 38282676, 2023). "Tumor expression of PRLR, STAT5 and JAK2 was read manually by pathologist that may have led to measurement error; therefore, future studies should consider using image analysis to reduce subjectivity." (PMID 36882838, 2023). "In multiple cancer models, azaspirans and their derivatives have been tested as inhibitors of some tyrosine kinase proteins related to tumor progression, such as atiprimod (JAK2/JAK3 inhibitor) and lestaurtinib (JAK2 inhibitor), which present different tumor inhibition mechanisms." (PMID 37299000, 2023). "The JAK2/STAT3 cascade plays a key role in many cellular processes, including growth, division, programmed cell death, immunological escape and resistance, and tumor angiogenesis." (PMID 36740668, 2023). "Notably, HERC2-positive tumor cells expressed higher IL-6/JAK/STAT3-related genes and STAT3-targeted genes than HERC2-negative tumor cells, which also indicated the regulatory role of HERC2 in JAK2/STAT3 signaling." (PMID 36721234, 2023). "As the JAK2 activity increases, it reciprocates the JAK/STAT turnover and simultaneously induces phosphorylation of STAT5, which is an important mediator for the micro-metastasis, tumour invasion and expansion." (PMID 37680708, 2023). "Among them, the JAK2/STAT3 pathway is a component of JAK/STAT signaling that is upregulated in a variety of tumor cells and is particularly involved in the development of some solid tumors through the regulation of tumor cell proliferation and apoptosis." (PMID 37063281, 2023). "Furthermore, we detected the protein levels of p‐JAK2 and p‐STAT3 in tumor tissues collected from HCC xenograft tumor models by IHC." (PMID 37563971, 2023). "JAK2 inhibitors were predicted as putative PITPNC1 inhibitors with antiproliferative effect and their combination with KRASG12C inhibitors elicited a substantial anti-tumour effect in LUAD and PDAC." (PMID 37210549, 2023).
tumor (continued). "Our analysis highlights that ASCETIC consistently identifies alterations in CALR, JAK2, and IDH1/2 genes as early events in tumor history, while NRAS represents an acquired secondary event, towards which evolutionary trajectories appear to converge during the progression of the disease." (PMID 37749078, 2023). "Cell-intrinsic, genetic characteristics of the respective cancer cells, such as 9p24.1 amplification leading to increased Janus kinase 2 (JAK2) and PD-L1 expression or oncogenic RAS stabilizing the Pdl1 mRNA, explain differences in PD-L1 expression among tumor types." (PMID 38102680, 2023). "In addition, silencing or mutation of genes involved in the IFN-γ pathway, such as JaK1/JaK2 and STATS, can suppress the anti-tumour effects of IFN-γ and PD-L1 expression in tumour cells." (PMID 37221594, 2023). "The Janus kinase 2/signal transducer and activator of transcription 3 (JAK2/STAT3) pathway is involved in different biological processes, such as immunity, cell division, cell death, and tumor formation." (PMID 37686148, 2023). "Among them, ERBB4 and NPM1 are presumably involved in cSCC tumorigenesis; in addition, GNAQ, GNAS, JAK2, NRAS, IDH2, and CTNNB1 may be related to tumor metastasis." (PMID 36780540, 2023). "To determine whether the activation is specific to JAK inhibition by ruxolitinib, we treated BMDMs with CM from 4T1 tumor cells in presence of Solcitinib and NVP-BSK805, inhibitors specific for JAK1 and JAK2 respectively." (PMID 37005447, 2023). "In addition, DOK7 overexpression also reduced the levels of p-JAK1, p-JAK2 and p-JAK3 in the tumor tissues." (PMID 38095644, 2023). "Fractions with the highest concentration of proanthocyanidin (PAC) inhibited cellular viability and reduced tumor volumes while also reducing p-JAK1, p-JAK2, p-JAK3, p-STAT1, p-STAT3, and p-STAT5 (although there was no change in total STATs, total JAKs were decreased)." (PMID 36355554, 2022). "P-Stat3 and p-Jak2 were induced by overexpression of miR-877-3p, and suppressed by knockdown of miR-877-3p in both SGC7901 and BGC823 cells, which was further validated by western blot analysis on the tumor samples derived from the mouse model." (PMID 35600882, 2022). "Thus, IL-6 induces the activation of its downstream cascade JAK2/STAT3 pathway, contributing to tumorigenesis by regulating cell cycle progression, angiogenesis and tumor cell escape of the immune system." (PMID 36591515, 2022). "Baicalin can reduce the m6A modification level of HKDC mRNA by inhibiting METTL3, which leads to the decrease of HKDC expression and the upregulation of HKDC/JAK2/STAT1/caspase-3 signaling pathway, and finally inhibits the invasion and metastasis of tumor cells." (PMID 35784761, 2022). "While Ruxolitinib (JAK1/JAK2 inhibitor) impaired murine CTL activity against tumor cells in vitro, neither pacritinib (JAK2 inhibitor) nor ruxolitinib interfered with the GVL effect in vivo in MHC-mismatched murine models." (PMID 35677056, 2022). "Therefore, mutations and deletions of proteins related to this pathway on tumor cells, such as JAK1 and JAK2, STAT1, and IRF1, the IFNγ receptor chain, can lead to resistance to immune checkpoint inhibitors." (PMID 36185620, 2022). "Similarly, the down-regulation of p-JAK2 and p-STAT3 in the tumor tissues of the mice co-treated with β-Ele and cisplatin were confirmed by IHC assay and H-score." (PMID 35909161, 2022). "JAK2/STAT3 signaling pathway, which is extremely related to cancer initiation, metastasis, progression, chemoresistance, and immune evasion, is assumed to be a central mediator of tumor-related immune suppression." (PMID 35606804, 2022). "The findings of the current study showed that FTO inhibited expression of APOE through IGF2BP2-mediated m6A modification and may inhibit glycolytic metabolism in PTC by modulating IL-6/JAK2/STAT3 signaling pathway, thus abrogating tumor growth." (PMID 35090515, 2022).
tumor (continued). "In addition, protein levels of “p-p38, p-JAK2, and p-STAT1” were downregulated in miR-195-5p-overexpressed PTC cells and tumor xenografts, whereas CircRNA NRIP1 upregulation reversed these effects." (PMID 36230649, 2022). "In addition, on the one hand, neutrophils/chemerin activated JAK2/STAT3 pathway and upregulated its down stream cycle-related proteins to promote tumor proliferation." (PMID 35155249, 2022). "Several reports demonstrated that PLA2R1 has an important role in regulating tumor-suppressive responses via activation of Janus kinase 2, yet these effects do not seem to be related to its sPLA2 binding properties." (PMID 35887380, 2022). "Importantly, Tris DBA downmodulated the expression of activated JAK1, JAK2, and STAT3, and Ki-67 in MM tumor tissues." (PMID 34771643, 2021). "Further, to assess whether SSFH/Cas9 inhibit by block IL-3/CD123 interaction and further interfere JAK2/STAT5 pathway, tumor tissues were collected and subjected to JAK2/STAT5 staining." (PMID 34121564, 2021). "Finally, in human NCI-H292 tumor epithelial cells, IFN-γ activates phospholipase C-γ (possibly via an upstream tyrosine kinase distinct from JAK1/JAK2) which induces the sequential activation of PKC-α c-Src and STAT1." (PMID 33668421, 2021). "Moreover, the expression of PD-L1, JAK2 phosphorylation and STAT1 phosphorylation (included S727 and Y701) were increased in MC38 tumor tissues from C57BL/6 mice after Foretinib treatment." (PMID 34307367, 2021). "Moreover, in preclinical models of JAK2/IDH-mutant MPNs, the combination of JAK2 and IDH inhibitors showed a strong inhibition of tumor growth and suppression of abnormal 2-hydroxyglutarate production." (PMID 34680226, 2021). "miR-204-5p is a tumor suppressor in HNSCCs, which inhibits tumor growth, metastasis, and stemness by suppressing the signal transducer and activator of transcription 3 (STAT3) signaling and EMT via targeting SNAI2, SUZ12, HDAC1, and JAK2." (PMID 33917482, 2021). "The Janus kinase 2 (JAK2)/signal transducer and activator of transcription 3 (STAT3) axis has been demonstrated to play a crucial role in the progression of HCC and is involved in the process of tumor metastasis." (PMID 34113574, 2021). "Besides, the protein levels of p-p38, p-JAK2 and p-STAT1 were remarkably down-regulated in miR-195-5p overexpressed PTC cells and tumor xenografts, whereas CircRNA NRIP1 up-regulation overturned the impacts." (PMID 34689819, 2021). "Interestingly, the combination of chemotherapy and momelotinib is a potent inhibitor of Jak2, and it suppresses CSC-like cells and reduces tumor burden in vHCC." (PMID 34199353, 2021). "Also, deletions of JAK2, CD274 and MYD88 genes, and amplification of FGFR4 and NPM1 genes, are also involved in clinical trials for other tumor types." (PMID 33668731, 2021). "Regarding potential mechanisms, leptin can activate the JAK2/STAT3, PI3K/Akt/mTOR, and extracellular regulated protein kinase (ERK) pathways by binding to its own receptors expressed in tumor cells and stromal components, including immune cells, endothelial cells and tumor-associated fibroblasts." (PMID 33842335, 2021). "Consistent with the results observed in vitro, we also found that the OCa tumor weight and volume of nude mice injected with lncRNA MALAT1 overexpression vector were enhanced and JAK2 protein level increased remarkably in comparison to the ginkgolic acid group." (PMID 34987594, 2021). "We also analyzed the JAK2/STAT3 pathway and EMT markers in the tumor samples by Western blot." (PMID 34895038, 2021). "Emerging evidence has suggested that the JAK2/STAT3 pathway participates in the regulation of angiogenesis 26, and blockade of the JAK2/STAT3 pathway could inhibit tumor growth." (PMID 33976735, 2021). "In addition, the protein expression levels of p-JAK2 (Y1007/1008) and p-STAT3 (Tyr705) in the tumor tissues of nude mice in the LNT group were significantly reduced by western blot." (PMID 34900727, 2021).
tumor (continued). "explored several HNSCC cell lines and found that the programmed death ligand-1 (PD-L1), which limits the function of activated T lymphocytes when they interact with the ICP receptor programmed death-1 (PD-1), is expressed by tumor cells in an EGFR- and JAK2/STAT1-dependent manner." (PMID 33718169, 2021). "Most importantly, pharmacological Jak2-Stat5 blockade inhibited CR growth of PC xenograft tumors after ENZ resistance developed and induced further cell death in patient-derived PCs treated with ENZ ex vivo in tumor explant cultures." (PMID 34680353, 2021). "In addition, it has been shown that the IL-6/JAK2/STAT3 pathway is significantly and preferentially activated in bCSCs with a basal-like phenotype in comparison with luminal-like tumor cell types." (PMID 33802575, 2021). "In particular, we minimize tumour volume and maximize the apoptotic potential by minimizing the Bcl-2 concentration and maximizing the BAX level while minimizing total injection amount of both IFN-β and JAK2 inhibitors (DDP)." (PMID 34631119, 2021). "Thus, resistance to HER2-TCB in different contexts results in the same defect: downmodulation of JAK2 and impaired IFN-γ signaling in tumor cells." (PMID 33623012, 2021). "Previous studies have suggested that JAK2/STAT3 pathway participates in the regulation of angiogenesis, and blockade of the JAK2/STAT3 pathway could inhibit tumor growth." (PMID 33976735, 2021). "Furthermore, we investigated the effect of nifuroxazide on IL-6/jak2/STAT3 signaling and the possible impact on tumor angiogenesis." (PMID 34833950, 2021). "The reason why we add a JNK inhibitor is because JNK signaling is also related to STAT3 activity, and is to confirm that the JAK2/STAT3 signaling pathway uniquely plays an important role in maintaining self-renewal and tumor initiating capacity of CSCs, and enhancing stemness characters." (PMID 32326231, 2020). "The increased serum IL-6 activated STAT3/c-MYC signaling in peripheral monocytes, enhanced the transcription of miR-25–3 p, suppressed PTPRO expression, promoted PD-L1 through both JAK2/STAT3/c-MYC and JAK2/STAT1 signaling, and promoted tumor growth by enhancing T-cell exhaustion." (PMID 32581055, 2020). "The pharmacological inhibition of Jak2/Stat3 leads to an antitumor immune response that enhances the efficacy of chemotherapy, suggesting that the oncogene PTEN is involved in immunomodulation of the tumor microenvironment through SASP." (PMID 32028565, 2020). "These assays indicated that the effect of Faecalibacterium prausnitzii on JAK2/STAT3 was mediated at least in part by IL-6 and the anti-tumor effect of Faecalibacterium prausnitzii may be through inhibition of the IL6/STAT3 pathway." (PMID 32272885, 2020). "In the tumor microenvironment, it induces EMT via the activation of the JAK2/STAT3 pathway." (PMID 32268527, 2020). "In further pre-clinical studies, co-treatment of cells with paclitaxel and a JAK2 inhibitor, NVP-BSK805, could significantly reduce STAT3 phosphorylation, and in vivo tumor growth, when compared with paclitaxel alone." (PMID 32328465, 2020). "Additionally, OPN as a tumor biomarker is induced through the TM4SF4/GSK3β/β-catenin axis, JAK2/STAT3, and FAK/STAT3 signaling, and is additionally regulated via formation of positive feedback autocrine loop that results in cells acquiring CSC-like properties." (PMID 31952344, 2020). "However, several promising potential therapy targets exist in the form of using neutralizing antibodies, JAK2/STAT3 pathway-specific inhibitors, and silencing the expression of pre-cancerous interleukins secreted by CAFs in the tumor microenvironment." (PMID 32268527, 2020). "AMPK suppresses tumor survival through inhibition of mTOR by increasing the expression of p-TSC2, a tumor suppressor gene, and leads to the inactivation of AKT and lipopolysaccharide (LPS)-induced IL-6/JAK2/STAT3 signaling in triple-negative breast cancer (TNBC)." (PMID 31952344, 2020).
tumor (continued). "We detected that MELK overexpression could induce M2 macrophage polarization via the miR-34a/JAK2/STAT3 pathway, contributing to doxorubicin chemoresistance in the tumor microenvironment." (PMID 32391256, 2020). "In the literature, the upregulation of PD-L1 in tumor cells is correlated with two mechanisms—the extrinsic pathway which depends on interferon gamma produced by NK and CD8+ T cells, and the intrinsic pathway which relies on the EGFR/JAK2 signaling pathway." (PMID 32872195, 2020). "The tumor cells with JAK1/JAK2 gene mutation were not sensitive to the killing effect of IFN, and the expression of PD‐L1 was downregulated, making the tumor cells resistant to PD‐1/PD‐L1 monoclonal antibody." (PMID 32875727, 2020). "Activation of the JAK2/Signal transducer and activators of transcription 3 (STAT3) signaling pathwayhas revealed to have vital roles of tumorigenesis and progression in different human tumor cell types." (PMID 34675459, 2020). "CDKs and tyrosine protein kinase JAK2 act as cellular oncoproteins and MAX as a tumor suppressor." (PMID 31803618, 2019). "In the preclinical stage, paclitaxel and Momelotinib (ATP-competitive inhibitor of JAK1/2, previously named CYT387) inhibited JAK2/STAT3 activation, reduced tumor burden, abrogated cancer stem cell expressions and prolonged disease-free survival in a murine xenograft model." (PMID 31861720, 2019). "Additionally, the results from western blot assays revealed that knockdown of HE4 obviously inhibited expression of p-JAK1, p-JAK2 and p-STAT3 in xenograft tumor tissues." (PMID 31477564, 2019). "Furthermore, we identified that the addition of a PDGFRβ inhibitor enhances the efficacy of combined MEK1/2 and JAK2 inhibition in vitro and significantly hampered TNBC syngeneic tumor growth in vivo through intratumoral CD8+ T cells infiltration." (PMID 30777101, 2019). "There was a decrease in pSTAT3+ tumor cells (JAK2 amplified and non-amplified) in biopsies after two cycles of ruxolitinib treatment, confirming on-target activity of the drug even in the presence of JAK2 amplification." (PMID 29761158, 2018). "Type I JAK2 inhibitors such as ruxolitinib bind within the ATP-binding pocket of the active conformation of JAK2, to compete with ATP, thereby inhibiting the phosphorylation of STAT5 and p-STAT5 signaling within tumor cells." (PMID 29487712, 2018). "The anti-tumor effect of GJXLT might also be related to the inhibition of p-STATS and VEGF expression in the JAK2/STAT3 pathway." (PMID 30271456, 2018). "Nonetheless, the 50% unresponsive mice group, presumably resistant to momelotinib treatment, that developed tumors showed levels of JAK2/STAT3 activation, c-Kit and Oct3/4 expression that were similar to their paclitaxel+ momelotinib counterparts in Phase 1 which also showed similar tumor burden." (PMID 29682172, 2018). "The anti-tumor effect of GJXLT might be related to the inhibition of p-STATS and VEGF expression in the JAK2/STAT3 pathway." (PMID 30271456, 2018). "However, if the suppression of an activated JAK2/STAT3 pathway can be sustained by momelotinib, tumor growth can be repressed which can result in a prolonged disease-free survival period." (PMID 29682172, 2018). "The JAK2/STAT signalling pathways is thus very important for cell growth and differentiation, and natural products that target JAK2/STAT have potential for the treatment of cancer and tumours." (PMID 29984230, 2018). "The increased leptin could bind to LepR and activate Jak2/STAT3 signaling in BMSCs, thus forming more BMAs and creating a positive feedback for tumor cells." (PMID 30013512, 2018). "When tumor cells were pretreated with Janus kinase 2 (JAK2) inhibitor, SHP2 depletion failed to induce HLA-ABC and PD-L1 expression." (PMID 28881828, 2017).